HSP90AA1 (heat shock protein 90 alpha family class A member 1)
Diseases named in the same sentence as HSP90AA1 in open-access papers (continued):
Sharing a sentence is not in itself a finding about the gene and the disease.
tumor (continued). "Conversely, the knockdown of HSP90AA1 in circRNF19A-aa-overexpressed 22Rv1 cells exhibited a partial inhibitory effect on tumor growth, while the knockdown of HSP90AA1 alone resulted in a marked reduction in tumor proliferation." (PMID 39567496, 2024). "We performed immunohistochemical experiments on the significantly differentially expressed gene, HSP90AA1, to verify the differential gene expression in tumor and peritumor tissues." (PMID 37291495, 2023). "The levels of HSP90AA1 in tumor and peritumor tissues were compared in HCC patients by immunohistochemical (IHC) staining, which showed that HSP90AA1 was overexpressed in tumor tissues." (PMID 37291495, 2023). "We conducted Western blot analysis to confirm the differential expression of HSP90AA1 between tumor and normal tissues." (PMID 37587188, 2023). "Similar to the mRNA levels, HSPA4, PANX1, and HSP90AA1 were significantly elevated in LUAD tumor tissues compared to normal tissues." (PMID 37259066, 2023). "Here, we report a novel mechanism by which NAT10-mediated mRNA ac4C-modified HSP90AA1 regulates metastasis and tumor resistance in ERS of HCC." (PMID 36765042, 2023). "The down-regulation of HSP90AA1 can achieve inhibition of tumor cell proliferation, migration and invasion." (PMID 37547757, 2023). "The key variations include loss of PTEN, copy gain of HSP90AA1, and mutations in FOXO3 or BCL2, all of which are well established to contribute to tumor cell growth and survival." (PMID 36831263, 2023). "HSP90AA1 plays an important role in the proliferation, differentiation, survival, and angiogenesis of tumor cells." (PMID 36744264, 2023). "HSP90AA1 can enter the nucleus, stimulate immune memory formation, and participate in tumor development in the extracellular environment." (PMID 35965557, 2022). "The top 3 hub-genes, namely AKT1, ESR1 and HSP90AA1, identified by protein–protein interaction network analysis using Tamarixetin targets, are known to play prominent roles in tumor progression." (PMID 35273218, 2022). "Another study found that HSP90AA1 protein product HSP90α is thought to play a key role in tumor invasion and migration regulation." (PMID 35330393, 2022). "The expression of HSP90AA1 in a variety of tumors was found to be correlated with tumor prognosis, immune cell invasion, immune checkpoint genes and a variety of signaling pathways, but the correlation was inconsistent among different tumors." (PMID 36158677, 2022). "HSP90AA1 can induce tumor angiogenesis by regulating the expression of vascular endothelial growth factor (VEGF) and promoting tumor proliferation and metastasis." (PMID 36675706, 2022). "Recent studies demonstrated that HSP90AA1 facilitated tumor progression, invasion, and chemoresistance." (PMID 35590292, 2022). "To explore possible roles of HSP90AA1 in carcinogenesis, we analyzed its expression distribution of HSP90AA1 gene in 33 tumor tissues and normal tissues." (PMID 36158677, 2022). "Newly formed HSP90AA1 can be secreted into the extracellular environment and the nucleus, stimulating the formation of immune memory and participating in tumor formation." (PMID 36686662, 2022). "The expression of HSP90AA1 is closely related to tumor proliferation, apoptosis, and the development of drug resistance." (PMID 35263200, 2022). "Extracellular heat shock protein 90α (HSP90AA1) has been widely reported to promote tumor cell migration and tumor metastasis in many tumors." (PMID 34876062, 2021). "Four heat shock proteins (Hspa5, Hsp90ab1, Hspa8 and Hsp90aa1) were included in the top candidate list and Hsp90ab1 was predicted to be one of the most influential tumor suppressors, as well as calreticulin (Calr) and peptidylprolyl isomerase B (Ppib)." (PMID 33859739, 2021). "Newly formed HSP90AA1 can be secreted into the extracellular environment and can also enter the nucleus to stimulate the formation of immune memory and participate in tumor formation." (PMID 34109171, 2021).
tumor (continued). "Further analysis of tumor patients revealed that HSP90AA1 was highly correlated with N and M stages, showing its distinguishing power for metastatic patients." (PMID 34109171, 2021). "To test the anti-tumor action of extracellular Hsp90ab1, we employed recombinant Hsp90ab1 (Hsp90 beta) together with recombinant Hsp90aa1 (Hsp90 alpha) as a control." (PMID 34830748, 2021). "To determine the roles of HSP90AA1 up-regulation in the immune-resistant phenotype of P3 tumor cells, we silenced HSP90AA1 in P3 cells using three kinds of siRNAs: siHSP90AA1 #1, #2, or #3." (PMID 31992715, 2020). "In our systematic analyses of various databases, we found that HSP90AA1 was significantly upregulated in HNSC patients, and its expression level was significantly associated with the tumor stage in HNSC patients." (PMID 32523426, 2020). "Consistently, silencing of HSP90AA1 reverses resistant phenotypes against to cognate CTLs of P3 tumor cells, indicating a crucial role of HSP90A in a tumor-intrinsic resistance to CTL." (PMID 31992715, 2020). "HSP90AA1 acts as a highly conserved chaperone protein and participates in tumor cell differentiation, proliferation, and angiogenesis." (PMID 32523426, 2020). "We also analyzed HSPH1, HSPD1, SERPINH1, HSPA4, and HSP90AA1 expression as a function of the HNSC tumor stage." (PMID 32523426, 2020). "Many of the client proteins regulated by HSP90AA1 are proto-oncogene products (such as c-MYC) or important signal transduction factors during tumor pathogenesis, which are closely related to the occurrence and development of tumors." (PMID 32576198, 2020). "Here, we report a crucial role of HSP90A at the crossroads between NANOG-TCL1A axis and multi-aggressive properties of immune-edited tumor cells by identifying HSP90AA1 as a NANOG transcriptional target." (PMID 31992715, 2020). "In BRAC tissues, the expression of HSP90AA1, HSP90AB1, and HSP90B1 was conformably correlated with the expression of biomarkers of some lineages of CD4+ helper T (Th) cells and tumor-associated macrophages (TAMs)." (PMID 33145341, 2020). "Using univariate Cox regression analysis followed by multivariate Cox regression analysis, we built a risk score formula comprising prognostic HSPs (HSPA2, DNAJC20, HSP90AA1, CCT1, CCT2) and tumor stage to identify high-risk and low-risk cases." (PMID 31101846, 2019). "By TUNEL staining, we found that the resected tumor tissues with HSP90AA1 shRNA transfection showed higher apoptosis than those with control shRNA transfection in response to chemotherapy." (PMID 30153855, 2018). "In non-tumor cell models such as fibroblasts, HSP90AA1 secretion was observed after hypoxia, which triggered increased mobility." (PMID 28468249, 2017). "Among them, nitric-oxide synthase regulator activity, referred to hsp90aa1 and hsp90ab1 proteins, is particularly interesting, since the nitric oxide (NO) pathway appears to play a key role in tumor angiogenesis and spread." (PMID 27050372, 2016). "Through the basis of annotation suggesting that PTK2, CTTSL1, TNC, ETS1 and HSP90AA1 were involved in tumor cell proliferation, prevent tumor cell from apoptosis and promote tumor cell invasion in oral carcinogenesis." (PMID 23405089, 2013). "Additionally, genes involved in the cellular response to stress were commonly upregulated in tumor C1 and C2 NK cells (HSP90AA1, HSPA1B, HSPH1, DNAJB1, PSMB9, CSTP1)." (PMID 41082397, 2026). "In addition, we constructed a mouse renal orthotopic xenograft tumor growth model to clarify the effect of HSP90AA1 overexpression on ccRCC development in vivo." (PMID 41507145, 2026). "Therefore, our above results revealed for the first time that HSP90AA1 acts as a tumor suppressor in ccRCC." (PMID 41507145, 2026). "By comparing tumor tissues to normal tissues, HSP90AA1 was increased." (PMID 40263268, 2025). "Similarly, G6PD and HSP90AA1 exhibited notably increased protein expression in tumor tissues compared to normal controls." (PMID 40299459, 2025).
tumor (continued). "According to network pharmacology and molecular docking, HSP90AA1 and TNF‐α may be implicated in the action of NF against the wasting of muscles in tumour‐bearing mice." (PMID 40170230, 2025). "Furthermore, our study elucidates the critical role of HSP90AA1 in shaping the Tumor Immune Microenvironment (TIME)." (PMID 41567202, 2025). "We elucidated that high intratumoral HSP90AA1 expression significantly correlates with advanced disease and poor survival, a phenomenon we attribute to “chaperone addiction” in aggressively proliferating tumor cells striving to maintain proteostasis." (PMID 41567202, 2025). "Inhibition of HSP90AA1 expression can reduce tumor cell proliferation." (PMID 40740310, 2025). "Collectively, these results demonstrate that HSP90AA1 is not only a supporter of tumor cell survival but also a master regulator of the inflammatory milieu that may facilitate immune evasion." (PMID 41567202, 2025). "HSP90AA1 expression in tumor cells promotes the progression of HNSCC." (PMID 38713284, 2024). "Notably, Hsp90aa1 is an isoform of the molecular chaperone Hsp90 which significantly regulates signal transduction, proliferation, cell cycle, apoptosis, and tumor progression." (PMID 39220589, 2024). "Moreover, experiments in vivo demonstrated that Aloin A effectively rescued muscle function and wasting by improving muscle quality, mean CSA, and distribution of muscle fibers by regulating HSP90AA1/AKT signaling in tumor-bearing mice." (PMID 38180061, 2023). "Hence, future studies shall achieve the prediction of LNMs and prognosis of HPSCC with HSP90AA1 as the tumor biomarker." (PMID 37547757, 2023). "Meanwhile, the proliferation, migration, and invasion, promoting cell apoptosis of tumor cells were significantly inhibited and suggested that HSP90AA1 may inhibit the metastasis of tumor cells by regulating EMT." (PMID 37547757, 2023). "However, there were strong correlations between the RNA expression of SCAN-TFs and HSP90AA1 in clinical tumor specimens." (PMID 36982267, 2023). "HSPA8 and HSP90AA1, representative molecular chaperones, have a wide variety of effects, such as prevention of unfolded-protein aggregation, chaperone-mediated autophagy, and promotion of tumor cell proliferation." (PMID 34151031, 2021). ", implying that HSP90AA1 contributes to tumor cell hyperproliferation." (PMID 35095481, 2021). "Similarly, one of the factors in the HSP90 family, HSP90AA1, has also been reported to function in tumor progression." (PMID 31803616, 2019). "NOD/SCID mices were inoculated with MG-63 tumor cells transfected with HSP90AA1 specific shRNA." (PMID 30153855, 2018). "Finally, HSP90AA1 was also shown to interact with PinX1, which mainly participates in stabilizing many proteins required for tumor growth." (PMID 28978030, 2017). "HSP90AA1 plays an important role in each step of the cell cycle and tumor formation." (PMID 24066008, 2013). "However, other studies have reported that HSP90AA1 can act as a tumor suppressor." (PMID 41507145, 2026). "Thus, our results suggested that HSP90AA1 acts as a tumor suppressor in ccRCC by regulating FBXO7." (PMID 41507145, 2026). "Our Protein–protein interaction (PPI) network analysis results demonstrated that the key target genes of FSH for anti-tumor treatment were AKT1, EGFR, BCL2, CTNNB1 and HSP90AA1." (PMID 40230723, 2025). "Functional validation confirmed that knockdown of HSP90AA1 significantly suppressed UVM cell proliferation, migration, invasion, and in vivo tumor growth." (PMID 41567202, 2025). "Among them, GPD2, GPI, HSP90AA1 and PGK2 are involved in promoting glycolysis and tumor cell proliferation." (PMID 39509399, 2024). "Among them, INHBA, HSP90AA1, and EIF2AK2 were significantly higher expressed in tumor samples than in normal samples." (PMID 39006030, 2024).
tumor (continued). "The five-gene signature’s expression was validated utilizing the TCGA database, with NT5E, HSP90AA1, and EIF2AK3 demonstrating elevated expression levels in tumor tissues, while PIK3CA and P2RX7 exhibited heightened expression in normal tissues." (PMID 38575204, 2024). "Demonstrated as potent enhancers of tumor and cellular survival in cellular stress, the upregulation of the epichaperome genes HSP90AA1, HSPH1, and HSPA8 promotes the equilibrium of radio- and chemoresistance seen in tumor and indirect cell dormancy." (PMID 38994941, 2024). "Compared to the control group after 48 h of treatment with TGT, the expression of genes JUN, TYMS, HSP90AA1, HDAC1, CDK1, and ESR1 was downregulated, which showed inhibitory effect on tumor cell proliferation." (PMID 38297292, 2024). "Among the five identified ICDGs, NT5E, HSP90AA1, and EIF2AK3 exhibited heightened expression levels in tumor tissues, while PIK3CA and P2RX7 demonstrated elevated expression levels in normal tissues." (PMID 38575204, 2024). "The expression of HMGN1, HSP90AA1, BCL2, and AGER was verified in TCGA and GTEx databases, and HMGN1, HSP90AA1 and AGER were found to be highly expressed in tumor tissues." (PMID 38713284, 2024). "We predicted the associated miRNAs of target hub genes, 12 for PPP2CA followed by 7 for HSP90AA1 and 4 for EFGR, which would be further analysed for their role in tumour expression or repression." (PMID 39434198, 2024). "RT-PCR experiments also demonstrate that TGT can promote anti-tumor immune response by downregulating the expression of C-JUN and HSP90AA1." (PMID 38297292, 2024). "Follow-up studies are urgently warranted to further validate the predictive value of HSP90AA1 and other ICDGs in HNSCC immunotherapy and the anti-tumor immune mechanism." (PMID 38713284, 2024). "In the cases of invasive BC from the TCGA database in UALCAN, the mRNA levels of AKT1, ESR1, HSP90AA1, CASP3, SRC, and MDM2 were significantly increased in tumor tissues." (PMID 36882618, 2023). "In the protein level, the gene expression of HSP90AA1, NFKB2, PTK2 was upregulated in tumor tissues, and CLU, JAK2, MAP3K5, and S100B were downregulated in the normal tissues." (PMID 36323529, 2023). "This study identified HSP90AA1 as a downstream target of NAT10-mediated mRNA ac4C modification in the regulation of HCC metastasis and ERS-related tumor resistance." (PMID 36765042, 2023). "Then, we picked out 8 HAIRGs (VEGFA, CTNNB1, PPARG, HSP90AA1, HMOX1, LGALS3, SPP1, and RAC1) from the 17 HAIRG model through the LASSO Cox regression, upregulated genes accounted for 7/8 in tumor tissue, which was shown by a heat map." (PMID 35069936, 2022). "Heat-shock proteins (HSPs) —also phosphorylating AKT—were upregulated in CLs and normal-like TN tumours; some of them—HSP90AA1 and HSP90B1—were also upregulated in basal-like TN tumours, and one—HSP90B1— was upregulated across all sample groups." (PMID 36220861, 2022). "HSP90AA1 promotes HCC invasion by promoting epithelial-mesenchymal transition and inhibiting tumor stem cell apoptosis." (PMID 36134033, 2022). "In our study, the HSP90AA1 knockdown inhibited the AKT1 and ERK pathways, which were over-activated in tumor tissues." (PMID 35095481, 2021).
tumor (continued). "In this study, we demonstrated the crucial role of HSP90A at the crossroads between NANOG signaling and the multi-aggressive properties of immune-edited tumor cells by identifying HSP90AA1 as a NANOG transcriptional target." (PMID 31992715, 2020). "In summary, our results indicate that HSPH1, HSPD1, SERPINH1, HSPA4, and HSP90AA1 are significantly upregulated in HNSC patients and their upregulation is negatively correlated with HNSC tumor stage." (PMID 32523426, 2020). "TCGA dataset mining was performed using UALCAN to shown that abnormal expression of the hub genes, including CDK1, VEGFA, PRDM10, RUNX1, CDK6, HSP90AA1, and MYC, were significantly up-regulated between ESCA primary tumor and normal tissues." (PMID 32662828, 2020). "Downregulating KIT with a siRNA or HSP90AA1 inhibitors effectively reduced phosphorylated KIT and downstream signaling, which induced cell death and tumor shrinkage in IM-resistant GIST48 and GIST430 cells." (PMID 31363162, 2019). "The up-regulated genes following treatment included heat shock family proteins such as HSP90AA1, HSPA8, DNAJB12, HSPA1L, DNAJA1, HSPA4L, consistently with other array studies in different tumor cell types." (PMID 20920318, 2010). "The study confirmed that HSP90AA1, as a DAMP released during ICD, contributes to the activation of immune responses through interaction with pattern recognition receptors, but paradoxically, also supports tumor immune evasion in certain settings." (PMID 41009692, 2025). "Targeting HSP90AA1 may offer a new strategy for modulating the UVM tumor immune microenvironment and overcoming tumor progression." (PMID 41567202, 2025). "Intriguingly, HSP90AA1 was enriched in CD4+ T-cell subsets and positively correlated with immune checkpoint molecules such as PD-L1, indicating a role in shaping the immunosuppressive tumor microenvironment." (PMID 41009692, 2025). "Therefore, we examined the inhibitory effect of HSP90AA1 expression in tumor cells on IFN-γ secretion by T cells; we confirmed the role of HSP90AA1 in the immunosuppressive phenotype of HNSCC." (PMID 38713284, 2024). "Besides, in mast cells, two NPA genes HSP90AA1 and HSP90AB1 were up-regulated in tumor tissues, whereas BIRC3 was down-regulated." (PMID 38149248, 2023). "The data revealed higher expression of HSP90AA1 in tumor tissues of LM patients as opposed to non-LM patients." (PMID 37547757, 2023). "Consistent with our hypothesis, the Aspiletreins bound to the targets with high affinity and likely inhibited the tumor-promoting functions of STAT3, VEGFA, HSP90AA1, and FGF2 or enhanced tumor-suppressing activity of IL2, or both." (PMID 36707691, 2023). "Consistent with the RT-PCR results, the expression of HSP90AA1 in tumor tissues of LM patients markedly surpassed that in the non-LM group." (PMID 37547757, 2023). "ENTPD1, IL17A, and P2RX7 were downregulated, while HSP90AA1, PIK3CA, and NT5E were upregulated, indicating that ENTPD1, IL17A, and P2RX7 might negatively affect tumor development and result in better outcome." (PMID 37587188, 2023). "Additionally, the expression of HSP90AA1 and HSP90AB1 was positively correlated with tumor purity; and the expression of HSP90AA1 was positively related to CD8+ T cells, macrophages, and neutrophils, but negatively correlated with CD4+ T cells." (PMID 35845599, 2022). "Heat shock protein 90 alpha family class A member 1 (HSP90AA1), a stress-inducible member of the HSP90 family, regulates a range of proto-oncogene products (such as c-Myc) or important signal transduction factors during tumor pathogenesis." (PMID 35590292, 2022).